LAPTM5 (lysosomal protein transmembrane 5)
Diseases named in the same sentence as LAPTM5 in open-access papers (continued):
Sharing a sentence is not in itself a finding about the gene and the disease.
cancer (19 papers, 2011 to 2025). A tumor composed of atypical neoplastic, often pleomorphic cells that invade other tissues. "Our results reveal a molecular mechanism underlying lung-specific metastasis and identify LAPTM5 as a potential therapeutic target for cancers with lung metastasis." (PMID 35842443, 2022). "Inactivation of LAPTM5 is associated with tumorigenesis in human cancers." (PMID 35984577, 2022). "Lastly, to test whether LAPTM5 is associated with self-renewal ability of cancer cells, we established the forced lung metastasis model by directly injecting Rencaluci and derivative cell lines into mouse tail vein and collected the lungs at different time points." (PMID 35842443, 2022). "These functional alterations of lysosome can contribute to pathologies related to CNS immunity, highlighting the significance of LAPTM5 beyond its roles in cancer." (PMID 39281638, 2024). "LAPTM5 overexpression in cancer cells induces lysosomal cell death through lysosomal destabilization." (PMID 35984577, 2022). "Most importantly, activation of LAPTM5 in lung metastasis is a common molecular event shared by several types of cancer types." (PMID 35842443, 2022). "Previous study has shown that the oncogene LAPTM5 promotes the malignant process of a variety of cancers and its high expression level strongly correlates with the poor prognosis of GBM patients." (PMID 35109832, 2022). "Here, we document a critical role of LAPTM5, which regulates the self-renewal and cancer stem cell-like traits of RCC cells in lung stroma, thus promoting lung-specific metastasis of RCC." (PMID 35842443, 2022). "Phenotypically, we founded that LAPTM5 contributed to the self-renewal and cancer stem cell-like traits of RCC cells in lung stroma by blocking the effect of lung stroma-derived BMPs." (PMID 35842443, 2022). "Lastly, elevation of LAPTM5 expression in lung metastases is a common phenomenon in multiple cancer types." (PMID 35842443, 2022). "LAPTM5 was reported to regulate T and B cell receptor signaling and the human cancer cell cycle and death." (PMID 34692792, 2021). "LAPTM5, which is localized in the lysosomal membrane, was downregulated in a variety of human cancer cells, suggesting that the inactivation of LAPTM5 plays a role in tumorigenesis." (PMID 32582531, 2020). "We first examined the expression status of LAPTM5 in 333 cell lines from 18 various types of human cancers in comparison with the expression levels of each corresponding normal tissue by qRT-PCR analysis." (PMID 27058622, 2016). "The Lysosome associated protein transmembrane (LAPTM) family is comprised of three members: LAPTM5, LAPTM4a and LAPTM4b, with the latter previously shown to be overexpressed in numerous cancers." (PMID 22096579, 2011). "Given the proposed connection between stemness and metastasis initiation, we next investigated whether LAPTM5 promotes lung metastasis by regulating cancer stem cell (CSC)-like traits of RCC cells." (PMID 35842443, 2022). "Our results suggested that LAPTM5 may be a potential therapeutic target for lung metastasis of multiple cancer types." (PMID 35842443, 2022). "In conclusion, these data demonstrated that the activation of LAPTM5 in lung metastases is a common molecular event shared by several types of human cancer, and that the LAPTM5/WWP2-based lysosomal regulatory pathway mediates the ubiquitination and degradation of BMPR1A." (PMID 35842443, 2022). "Expression level of LAPTM5 is frequently decreased in numerous cancer cell lines." (PMID 35984577, 2022). "Low expression of LAPTM5 in cancer patients is correlated with poor prognosis." (PMID 35984577, 2022). "In contrast, LAPTM5 has a lower expression in other cancer types, such as LUAD, HNSC, and LUSC." (PMID 33521125, 2021). "A previous study found that LAPTM5 functions mainly in immune cells and cancer cells." (PMID 34692792, 2021). "In addition, we found that LAPTM5 is highly expressed in some cancer types, such as ESCA, KIRP, and KIRC." (PMID 33521125, 2021).
cancer (continued). "In TGCT, we found abnormal high expression of LAPTM5 in cancer samples." (PMID 33521125, 2021). "This suggests that the LAPTM5 gene plays different biological roles in different cancer types." (PMID 33521125, 2021). "Thus, further validations including somatic mutation will be required for understanding molecular mechanism for inactivation of LAPTM5 gene in human cancers." (PMID 27058622, 2016). "We next examined whether lysosomal destabilization is induced by overexpression of LAPTM5 in other types of cancer cell lines, as is in NB cells." (PMID 27058622, 2016). "Moreover, we observed that LAPTM5 expression was frequently decreased at the transcriptional level in various types of human cancer cells, similar to NB cells." (PMID 27058622, 2016). "Thus, identifying the physiological and cellular conditions of LAPTM5 accumulation-mediated cell death will be essential to further understand the biological significance of this type of cell death in human cancers." (PMID 27058622, 2016). "Furthermore, we showed that overexpression of LAPTM5 in several cancer cells induces lysosomal cell death due to lysosomal destabilization, indicated by leakage of lysosomal cathepsin D into the cytosol as well as impairment of autophagy." (PMID 27058622, 2016). "However, studies assessing LAPTM5 function in cancer pathology are still scarce." (PMID 39753521, 2025). "Also, the expression of LAPTM5 closely related to tumorigenesis in many human cancers." (PMID 33392203, 2020). "Finally, our findings suggest that the transcriptional down-regulation of LAPTM5 may lead to the repression of LAPTM5 accumulation-mediated cell death in human cancers, including ESCC and NSCLC." (PMID 27058622, 2016). "This suggests that LAPTM5-induced cell death may widely occur in various human cancers." (PMID 27058622, 2016). "However, the pathological expression and role of LAPTM5 in other types of human cancers remain largely unknown." (PMID 27058622, 2016). "However, the pathological expression and role of LAPTM5 in other types of human cancers are largely unknown." (PMID 27058622, 2016). "Here the authors show that LAPTM5 contributes to lung-specific metastasis of RCCs by suppressing BMP signalling and thus, enhancing self-renewal and cancer stem cell-like traits of RCCs." (PMID 35842443, 2022). "For example, the LAPTM5-a7 transcript (transcribed from the LAPTM5 gene) and CORO1A-u2 transcript (an unannotated transcript from the CORO1A gene) are exclusively expressed in cancer cell lines derived from haematopoietic and lymphoid lineages." (PMID 36357395, 2022). "In addition, the mRNA data in the Cancer Cell Line Encyclopedia database showed that the expression of C1QC, CSF1R, LAPTM5 and SLCO2B1 mRNA was significantly lower in LUSC cell lines (n=23) compared to lymphoid cell lines (n=167)." (PMID 33428598, 2021). "CXCL8 and LAPTM5 proteins have been reported to promote cell activity, TMEM156 and LGALS1 proteins enhance cell invasion, VIM and LGALS1 proteins induce cell migration, FABP5 and SRGN proteins activate cancer metastasis, and the DEFB4A protein regulates immunity in human cancers." (PMID 35632763, 2022).
infection (4 papers, 2009 to 2023). The state of being infected such as from the introduction of a foreign agent such as serum, vaccine, antigenic substance or organism. "Here, using proteomics and cell-based assays, the authors show that HIV accessory protein Vpr mediates the degradation of host lysosomal-associated transmembrane protein 5 (LAPTM5) in monocyte-derived macrophages (MDM) to enhance infection in macrophages." (PMID 34140527, 2021). "The overexpression of LAPTM5 resulted in a 257- to 664-fold reduction in infection by CXCR4-, CCR5-, or dual-tropic Vpr-defective HIV-1, whereas the production of HIV-1 capsid was intact." (PMID 34140527, 2021). "Strong expression of the LAPTM5 protein was detected at 4 days, rather than at 2 days, after infection in three cell lines, GOTO, IMR32, and SH-SY5Y, and cell survival rates decreased in a dose-dependent manner on adenovirus-LAPTM5 (Ad-LAPTM5) infection." (PMID 19787053, 2009). "Four days after the infection, LAPTM5-positive vesicles were remarkably accumulated as larger entities in dying cells and colocalized with neither the Golgi apparatus nor LAMP2-positive lysosomes." (PMID 19787053, 2009). "Moreover, a remarkable increase in the number of dead cells with an increase in LAPTM5 protein level was observed at 4 days, after infection with Ad-LAPTM5, compared with adenovirus-LacZ (Ad-LacZ), in all cell lines." (PMID 19787053, 2009). "The exogenously expressed LAPTM5 was localized to vesicles and exhibited a punctuate pattern, and the LAPTM5-positive vesicles did not colocalize with the Golgi apparatus, but partially colocalized with LAMP2-positive lysosomes 1 day after the infection with Ad-LAPTM5." (PMID 19787053, 2009). "LAPTM5 protein was remarkably accumulated as large vesicles in Ad-LAPTM5-infected GOTO cells treated with 10 nM Baf.A1 or 10 μM ALLN for one day, similar to the pattern observed 4 days after the infection with Ad-LAPTM5." (PMID 19787053, 2009). "To validate whether Vpr induces LAPTM5 degradation, we infected MDMs with wild-type or Vpr-defective HIV-1AD8 in the presence or absence of Efavirenz (EFV) or raltegravir, which block HIV-1 productive infection." (PMID 34140527, 2021). "The infected cell population were measured in this single-cycle infection system, and we found that Vpr did not alter the level of gp120-containing virions in MDM culture in either low- or high-dose infection in the absence of LAPTM5, and the production of virion capsid was not affected." (PMID 34140527, 2021). "Moreover, we found evidence that LAPTM5 can target HIV-2 and the primate lentiviruses SIVmac239 and SIVagm but not MLV and FIV to restrict host infection, raising the possibility that LAPTM5 has a broader role in innate antiviral immunity against primate lentiviruses." (PMID 34140527, 2021).
neurological disease (3 papers, 2019 to 2026). "Lysosomal-associated protein transmembrane (LAPTM) family members-LAPTM4A, LAPTM4B, and LAPTM5-regulate lysosomal integrity, autophagy-lysosome flux, lipid homeostasis, and immune signaling, pathways increasingly implicated in neurological disease." (PMID 41666016, 2026). "We chose Alox5ap and Laptm5 to illustrate that expression profiles for the microglial gene module were similar irrespective of whether a gene has an established role in neurologic disease (e.g., Trem2 and Alox5ap) or limited to no known role (e.g., Laptm5) in neurologic disease." (PMID 31214167, 2019).
cardiovascular diseases (2 papers, 2021 to 2025). "In addition, recent studies have found that LAPTM5 is involved in the regulation of several signaling pathways, including nuclear factors-κB (NF-κB), transforming growth factor β (TGFβ)-Smads, phosphoinositide 3-kinase (PI3K)-AKT, and MAPKs, which are associated with cardiovascular diseases." (PMID 34692792, 2021).
metabolic disorders (1 paper, 2023). "Taken together, these findings strongly suggested that LAPTM5 has a good prospect of serving as a therapeutic target for the treatment of NASH and metabolic disorders." (PMID 37156795, 2023).
LAPTM5 also shares sentences with these, for which no sentence is quoted: hepatocellular carcinoma (3 papers); Clear Cell Renal Cell Carcinoma (2); Hypertension (2); non-small cell lung carcinoma (2); acute lymphoblastic leukemia (1); acute T cell leukemia (1); autoimmune thyroid disease (1); cervical cancer (1); cholestasis (1); chronic myelogenous leukemia (1); colon adenocarcinoma (1); colon cancer (1); colorectal cancer (1); Deficiencies (1); fetal growth restriction (1); germ cell tumor (1); hypertrophy (1); Insulin resistance (1); leukemia (1); mantle cell lymphoma (1); myositis (1); neurodegenerative disease (1); oral cancer (1); osteosarcoma (1); pancreatic cancer (1); pigmented villonodular synovitis (1); promyelocytic leukemia (1); Seizure (1); Sepsis (1); steatosis (1).
A further 1 disease shares a sentence with LAPTM5 in 1 paper.